PABPN1 (poly(A) binding protein nuclear 1)
Description:
Involved in the 3'-end formation of mRNA precursors (pre-mRNA) by the addition of a poly(A) tail of 200-250 nt to the upstream cleavage product (By similarity). Stimulates poly(A) polymerase (PAPOLA) conferring processivity on the poly(A) tail elongation reaction and also controls the poly(A) tail length (By similarity). Increases the affinity of poly(A) polymerase for RNA (By similarity). Is also present at various stages of mRNA metabolism including nucleocytoplasmic trafficking and nonsense-mediated decay (NMD) of mRNA. Cooperates with SKIP to synergistically activate E-box-mediated transcription through MYOD1 and may regulate the expression of muscle-specific genes. Binds to poly(A) and to poly(G) with high affinity (By similarity). May protect the poly(A) tail from degradation (By similarity). Subunit of the trimeric poly(A) tail exosome targeting (PAXT) complex, a complex that directs a subset of long and polyadenylated poly(A) RNAs for exosomal degradation. The RNA exosome is fundamental for the degradation of RNA in eukaryotic nuclei. Substrate targeting is facilitated by its cofactor MTREX, which links to RNA-binding protein adapters.
Synonyms: PABP-2; PABII; PAB2; PABP2; OPMD
Tractability: PROTAC: ubiquitination databases record sites on it; its protein half-life has been measured.
Gene: Protein-coding gene on chromosome 14 (23,321,457 to 23,326,163, forward strand). Ensembl gene ENSG00000100836.
Subcellular location: Nucleus; Cytoplasm; Nucleus speckle
Subcellular location (Human Protein Atlas): Nuclear speckles; Nucleoplasm
Pathways (Reactome):
Metabolism of RNA: Nuclear RNA decay; Processing of Intronless Pre-mRNAs; mRNA 3'-end processing; mRNA Polyadenylation
Disease: Dengue Virus-Host Interactions; Inhibition of Host mRNA Processing and RNA Silencing
Developmental Biology: Z-decay: degradation of maternal mRNAs by zygotically expressed factors
Gene expression (Transcription): RNA Polymerase II Transcription Termination
Gene Ontology:
Molecular function: protein binding; RNA binding; RNA polymerase binding; nucleic acid binding
Biological process: poly(A)+ mRNA export from nucleus; cellular response to lipopolysaccharide; MAPK cascade; muscle contraction; positive regulation of polynucleotide adenylyltransferase activity; RNA catabolic process; RNA processing
Cellular component: cytoplasm; nuclear inclusion body; nuclear speck; nucleoplasm; nucleus; ribonucleoprotein complex
Genetic constraint (gnomAD): Loss-of-function variants: 5 observed, 28.5 expected, observed/expected ratio (o/e) 0.18, 90% interval 0.091 to 0.37. The upper end of that interval is the gene's LOEUF score, 0.37, which puts it in group 1 of 6, group 1 being the genes least tolerant of losing a copy. Missense variants: 267 observed, 334.89 expected, observed/expected ratio (o/e) 0.8, 90% interval 0.72 to 0.88. Synonymous variants: 155 observed, 125.53 expected, observed/expected ratio (o/e) 1.23, 90% interval 1.08 to 1.41.
Homologues: Orthologues: pig PABPN1 (100% identical), guinea pig PABPN1 (98% identical), rabbit PABPN1 (97% identical), rat Pabpn1 (93% identical), mouse Pabpn1 (93% identical), tropical clawed frog pabpn1 (71% identical), dog PABPN1 (70% identical), zebrafish pabpn1 (59% identical), Drosophila melanogaster Pabp2 (43% identical), Caenorhabditis elegans pabp-2 (35% identical). Paralogues in human: PABPN1L (39% identical).
Diseases named in the same sentence as PABPN1 in open-access papers:
PABPN1 is named in the same sentence as 72 diseases in open-access papers, as found by Europe PMC text mining. Sharing a sentence is not in itself a finding about the gene and the disease. The quoted sentences say what the papers report.
oculopharyngeal muscular dystrophy (66 papers, 2009 to 2026). Oculopharyngeal muscular dystrophy (OPMD) is an adult-onset progressive myopathy characterized by progressive eyelid ptosis, dysphagia, dysarthria and proximal limb weakness. "For instance, mutations in the PABPN1 gene have been linked to oculopharyngeal muscular dystrophy (OPMD), an autosomal dominant neuromuscular disease caused by an abnormal N-terminal alanine extension." (PMID 40282297, 2025). "Several decades ago, mutations in the PABPN1 gene were identified as the underlying cause of Oculopharyngeal Muscular Dystrophy (OPMD), impacting a specific group of skeletal muscles." (PMID 40607380, 2025). "Mutations of PABPN1 caused by expansions of (GCN) triplet at the 5’-end of CDS result in with Oculopharyngeal muscular dystrophy." (PMID 40575986, 2025). "Expanded homorepeats have been associated with neurodegenerative disease and a modest alanine expansion in exon 1 of the poly (A) binding protein, nuclear 1 (PABPN1) gene is implicated in oculopharyngeal muscular dystrophy." (PMID 39342265, 2024). "Poly(A)-binding protein nuclear 1 (PABPN1) is an RNA-binding protein localized in nuclear speckles, while its alanine (Ala)-expanded variants accumulate as intranuclear aggregates in oculopharyngeal muscular dystrophy." (PMID 37422193, 2023). "Oculopharyngeal muscular dystrophy (OPMD) is caused by polyalanine expansion in nuclear protein PABPN1 [poly(A) binding protein nuclear 1] and characterized by muscle degeneration." (PMID 36901738, 2023). "We also show that oculopharyngeal muscular dystrophy (OPMD) mutations engender a switch from autophagosome stimulation to autophagosome inhibition by impairing PABPN1 and HNRNPQ control of the level of ULK1." (PMID 37559347, 2023). "As other examples, mutations in PABPN1 have been linked to oculopharyngeal muscular dystrophy (OPMD)." (PMID 34948199, 2021). "The small alanine expansions in the PABPN1 protein are known to cause oculopharyngeal muscular dystrophy, resulting in the intranuclear accumulation of PABPN1 in skeletal muscle." (PMID 34069857, 2021). "BCL2L2-PABPN1 is a paralog of PABPN1, which is associated with the development of oculopharyngeal muscular dystrophy, a disease characterized by muscular weakness in eyelids, pharyngeal musculature, and limbs." (PMID 34440365, 2021). "An expansion mutation in PABPN1 is the genetic cause for oculopharyngeal muscular dystrophy (OPMD), a late onset myopathy that is characterized by muscle wasting (reviewed in: Brais, 2009)." (PMID 33077830, 2020). "For example, mutations in PABPN1 causes oculopharyngeal muscular dystrophy (OPMD, OMIM #164300), characterized by progressive degeneration of muscles in adults." (PMID 29751519, 2018). "An expansion mutation in PABPN1 (expPABPN1) is the genetic causes for Oculopharyngeal muscular dystrophy (OPMD)." (PMID 29088723, 2017). "A mutated PABPN1 is the root cause of OPMD (oculopharyngeal muscular dystrophy) in humans, a late onset muscle disease associated with progressive ptosis of the eyelids, and dysphagia." (PMID 26527730, 2016). "Oculopharyngeal muscular dystrophy (OPMD) is caused by trinucleotide repeat expansion mutations in Poly(A) binding protein 1 (PABPN1)." (PMID 23793615, 2013). "A detailed understanding of the role of PABPN1 in gene expression is significant, as the human genetic disorder oculopharyngeal muscular dystrophy (OPMD) is linked to mutations in the PABPN1 gene." (PMID 23166521, 2012). "Our discovery that PABPN1 functions in the regulation of noncoding RNAs raises the possibility that oculopharyngeal muscular dystrophy, a disease associated with mutations in the PABPN1 gene, is caused by defective expression of noncoding RNAs." (PMID 23166521, 2012). "Oculopharyngeal muscular dystrophy (OPMD) is a late-onset progressive muscle disorder caused by a poly-alanine expansion mutation in the Poly(A) Binding Protein Nuclear 1 (PABPN1)." (PMID 21798095, 2011).
oculopharyngeal muscular dystrophy (continued). "Polyalanine expansions in the poly(A)-binding protein nuclear 1 (PABPN1) gene causes oculopharyngeal muscular dystrophy (OPMD)." (PMID 19641605, 2009). "Ala-expanded PABPN1 is able to form protein aggregates in nucleus, which may cause an autosomal-dominant disease, oculopharyngeal muscular dystrophy (OPMD)." (PMID 37422193, 2023). "Additionally, oculopharyngeal muscular dystrophy, which is a late-onset PA disease, is caused by PABPN1." (PMID 34873226, 2021). "Mutations in PABPN1 can also cause oculopharyngeal muscular dystrophy (OPMD)." (PMID 33526057, 2021). "Oculopharyngeal muscular dystrophy is caused by trinucleotide repeat expansions in the PABPN1 gene." (PMID 28361972, 2017). "Also, 6AP & GA showed benefit in a Drosophila-based model of OPMD (Oculopharyngeal muscular dystrophy), an inherited dominant myodegenerative disease caused by extension of a polyalanine tract in PABPN1 protein resulting in amyloid fiber accumulation." (PMID 27633137, 2016). "Moreover, trinucleotide repeat expansion of the PABPN1 gene is associated with oculopharyngeal muscular dystrophy (OMPD)." (PMID 26765774, 2016). "Polyalanine expansion in PABPN1 causes oculopharyngeal muscular dystrophy, OPMD." (PMID 19641605, 2009). "Oculopharyngeal muscular dystrophy (OPMD) is a late-onset disease caused by modest alanine expansion at the amino terminus of the nuclear polyadenosine RNA binding protein PABPN1." (PMID 41587185, 2026). "Autosomal dominant (and more rarely homozygous recessive) nucleotide-repeat expansion mutations in PABPN1, encoding polyadenylate-binding nuclear protein 1, are linked to oculopharyngeal muscular dystrophy (OPMD), a late-onset muscular dystrophy subtype." (PMID 40268053, 2025). "Oculopharyngeal muscular dystrophy (OPMD) has been linked to a GCG expansion in the n-terminus of the PABPN1 gene." (PMID 38002994, 2023). "Oculopharyngeal muscular dystrophy (OPMD) is caused by GCN repeat expansion in PABPN1 and presents with asymmetric ptosis and dysphagia that only manifests in adulthood, usually presenting in the fourth to sixth decade." (PMID 38132285, 2023). "Oculopharyngeal muscular dystrophy (OPMD) is caused by expansion of a triplet repeat in the PABPN1 gene resulting in nuclear protein aggregations." (PMID 32560344, 2020). "Oculopharyngeal muscular dystrophy (OPMD) is a genetic disease with a predominantly autosomal dominant pattern, linked to the PABPN1 gene." (PMID 26616227, 2017). "Since the identification of poly-alanine expanded poly(A) binding protein nuclear 1 (PABPN1) as the genetic cause of oculopharyngeal muscular dystrophy (OPMD), considerable progress has been made in our understanding of the pathogenesis of the disease." (PMID 26414348, 2015). "Interestingly, an N-terminal alanine expansion in PABPN1 that is thought to cause oculopharyngeal muscular dystrophy cannot completely rescue the effects of PABPN1 depletion, suggesting that this pathway may have relevance to disease." (PMID 25896913, 2015). "In mouse models of oculopharyngeal muscular dystrophy (OPMD), linked to an abnormal expansion of a polyalanine tract in PABPN1, oral administration of trehalose attenuated muscle weakness and reduced mutant PABPN1 aggregation in skeletal muscle." (PMID 25122660, 2015). "Oculopharyngeal muscular dystrophy (OPMD) is another triplet expansion disease which results from short expansions of a GCN repeat in the gene encoding poly(A) binding protein nuclear 1 (PABPN1)." (PMID 25816335, 2015). "In oculopharyngeal muscular dystrophy (OPMD), an expansion of an alanine tract at the N-terminus of poly(A)-binding protein nuclear 1 (PABPN1) causes muscle symptoms." (PMID 23815790, 2013). "The ninth is the ubiquitous RNA binding protein PABPN1 which is associated with the late onset disease oculopharyngeal muscular dystrophy (OPMD)." (PMID 23505376, 2013).
oculopharyngeal muscular dystrophy (continued). "Autosomal dominant oculopharyngeal muscular dystrophy (OPMD) is caused by a poly-alanine repeat expansion mutation in the gene encoding for Poly(A) Binding Protein Nuclear 1 (PABPN1)." (PMID 23793615, 2013). "Mutations in the PABPN1 gene, which encodes poly(A)-binding protein nuclear 1 (PABPN1), are shown to cause oculopharyngeal muscular dystrophy, a late-onset disorder with an unclear molecular basis." (PMID 40870034, 2025). "In oculopharyngeal muscular dystrophy (OPMD), an alanine expansion mutation in PABPN1 converts liquid‐like condensates to solid‐like aggregates, sequestering CFIm25 and causing aberrant APA." (PMID 40804711, 2025). "Additionally, testing for dynamic mutations in the poly-adenine-binding protein nuclear 1 (PABPN1) gene, which is associated with oculopharyngeal muscular dystrophy (OPMD), revealed normal GCN repeat numbers." (PMID 40084170, 2025). "Reduced PABPN1 levels were also reported in oculopharyngeal muscular dystrophy (OPMD), an adult-onset autosomal dominant myopathy." (PMID 38213032, 2024). "Oculopharyngeal muscular dystrophy (OPMD) results from a trinucleotide repeat expansion in the PABPN1 gene." (PMID 39501809, 2024). "Mutation of PABPN1 gene leads to oculopharyngeal muscular dystrophy (OPMD) and myotonic dystrophy." (PMID 36879298, 2023). "In the case of oculopharyngeal muscular dystrophy (OPMD), which is caused by trinucleotide repeat expansion in the poly A-binding protein nuclear 1 (PABPN1) gene, patients suffer from late onset of ptosis, swallowing difficulties, and formation of nuclear aggregates in skeletal muscles." (PMID 36992407, 2023). "Interestingly, the levels of functional PABPN1 have before been linked to global shifts from distal to proximal pA sites in cells from oculopharyngeal muscular dystrophy (OPMD) patients." (PMID 28453393, 2017). "For instance, an N-terminal alanine expansion in PABPN1 leads to oculopharyngeal muscular dystrophy (OPMD)." (PMID 25896913, 2015). "Oculopharyngeal muscular dystrophy (OPMD) is a late-onset, progressive muscle disorder caused by the abnormal expansion of a poly-alanine expansion mutation in the poly(A) binding protein nuclear 1 (PABPN1) gene." (PMID 26414348, 2015). "The disease oculopharyngeal muscular dystrophy (OPMD) is histochemically characterized by amyloid-like intranuclear inclusions consisting mainly of the nuclear RNA binding protein PABPN1." (PMID 21124848, 2010). "It was suggested that this regulation may be relevant to the etiology of human disease oculopharyngeal muscular dystrophy (OPMD), which is caused by an expansion mutation in the polyalanine repeat in the N-terminus of PABPN1." (PMID 25906188, 2015). "BACKGROUND: Oculopharyngeal muscular dystrophy (OPMD) is a late-onset autosomal dominant myopathy, caused by a (GCN)n/polyalanine repeat expansion in the PABPN1 gene." (PMID 42157275, 2026). "After the discovery of exonic GCG/GCA repeats in PABPN1 encoding polyalanine stretch in oculopharyngeal muscular dystrophy (OPMD), OPDM was clinically and genetically recognized as a distinct disease from OPMD." (PMID 36670296, 2023). "PABPN1 is decreased in muscles from oculopharyngeal muscular dystrophy (OPMD) patients and aged people, and its reduced level is associated with muscle weakness." (PMID 36552825, 2022). "In skeletal muscles PABPN1 levels reduce with age and a greater decrease in found in Oculopharyngeal muscular dystrophy (OPMD)." (PMID 29088723, 2017). "Oculopharyngeal muscular dystrophy (OPMD), a late-onset disorder characterized by progressive degeneration of specific muscles, results from the extension of a polyalanine tract in poly(A) binding protein nuclear 1 (PABPN1)." (PMID 25816335, 2015). "Furthermore, alanine-expanded mutant PABPN1 leads to the formation of toxic aggregates, resulting in oculopharyngeal muscular dystrophy (OPMD)." (PMID 40052530, 2025).
oculopharyngeal muscular dystrophy (continued). "The wild‐type Poly(A) binding protein nuclear 1 (PABPN1) forms benign nuclear aggregates, whereas a short trinucleotide expansion leads to the formation of pathogenic aggregates, a hallmark of Oculopharyngeal Muscular Dystrophy (OPMD)." (PMID 40552959, 2025). "Oculopharyngeal muscular dystrophy (OPMD) is a late-onset, mostly autosomal dominant muscular disorder, caused by the expansion of the trinucleotide repeat GCG in the 5′ end of the poly-A binding protein nuclear 1 (PABPN1) gene." (PMID 38607035, 2024). "Here, we uncover regulatory pathways of starvation‐induced autophagy by the RNA‐binding proteins, heterogeneous nuclear ribonucleoprotein Q (HNRNPQ) and poly(A) binding protein nuclear 1 (PABPN1), and showed that these pathways are perturbed by oculopharyngeal muscular dystrophy (OPMD) mutations." (PMID 37559347, 2023). "For instance, nuclear aggregates containing polyadenylate-binding nuclear protein 1 (PABPN1), the responsible molecule of oculopharyngeal muscular dystrophy, were detected in the patients." (PMID 37683014, 2023). "The downregulation of PABPN1 has also been reported in oculopharyngeal muscular dystrophy (OPMD)." (PMID 33467093, 2021). "For example, wild-type PABPN1 forms dynamic nuclear speckles with the assistance of poly(A) RNAs, whereas Ala expansion of PABPN1 results in the formation of aggregates, which are involved in the disease progression of oculopharyngeal muscular dystrophy (OPMD)." (PMID 39327933, 2024). "Beyond DM1, other muscular dystrophies, such as Facioscapulohumeral Dystrophy (FSHD) and Oculopharyngeal muscular dystrophy (OPMD), show dysregulation of mitochondrial protein import genes, such as the protein translocase ANT1 and PABPN1 (part of the TIM-23 complex), respectively." (PMID 35328504, 2022). "Given that PABPN1 is more likely to recognize and suppress the usage of weak proximal and non-canonical PASs in oculopharyngeal muscular dystrophy, we assessed whether PABPN1 diminishes the proximal PASs usage in cancer cells." (PMID 36879298, 2023).
cervical carcinoma (10 papers, 2017 to 2025). A carcinoma arising from either the exocervical squamous epithelium or the endocervical glandular epithelium. "For example, circPABPN1 regulates the linear PABPN1 through binding to HuR in human cervical carcinoma cells." (PMID 34420031, 2021). "CircPABPN1 is reported to sequester HuR, thereby serving as a decoy for HuR and impairing PABPN1 translation in cervical cancer cells." (PMID 34055896, 2021). "In human cervical carcinoma, high levels of circPABPN1 suppressed HuR binding to PABPN1 mRNA, inhibiting PABPN1 translation and resulting in decreased cell proliferation." (PMID 34202482, 2021). "Similarly, circPABPN1 suppressed the binding of HuR to PABPN1 mRNA and the translation level of PABPN1 by binding to HuR in human cervical carcinoma HeLa cells." (PMID 37002786, 2023). "It was demonstrated that hsa_circ_0031288, renamed circPABPN1 (poly(A) binding protein nuclear 1) as it rose from the PABPN1 pre-mRNA, could bond with ELAV-like RBP 1 (HuR) to prevent HuR binding to PABPN1 mRNA and reduce PABPN1 translation in human cervical carcinoma HeLa cells." (PMID 28928231, 2017). "For example, in HeLa cells of cervical cancer, the RNA binding protein HuR can promote the translation of PABPN1, and circPABPN1 (hsa_circ_0031288) can bind to HUR, which reduced the binding of HUR to PABPN1 mRNA and inhibited protein expression." (PMID 35682879, 2022). "Some researchers found that HuR didn’t affect circPABPN1 expression in cervical cancer, but increased circPABPN1 could inhibit the binding of HuR to PABPN1 (poly(A) binding protein nuclear 1) mRNA." (PMID 36091137, 2022).